CCL8 (C-C motif chemokine ligand 8)
Diseases named in the same sentence as CCL8 in open-access papers (continued):
Sharing a sentence is not in itself a finding about the gene and the disease.
tumor (continued). "To address whether CCL8 could induce the onset of cancer cell clusters, as predicted from in vitro model, we orthotopically implanted MCF7 cells with or without THP-1-derived M2-like macrophages into nu/nu mice and evaluated the onset changes of the tumor incidence upon blocking of CCL8." (PMID 35680853, 2022). "However, CCL8 expression was not different between WT and Apelin-KO mice in other tumor-associated cell types, including the MC38 cancer cells, CD45+ CD31− immune cells and CD45− CD31− stromal cells." (PMID 34234274, 2021). "Results of GO enrichment analysis and KEGG pathways revealed that CCL8 and CCL21 mainly function in chemokine signaling pathway, G protein-coupled receptor and inflammatory response, which are associated with BC carcinogenesis, tumor immune escape and chemoresistance." (PMID 33146700, 2020). "After correcting for gender, race and tumor purity, we identified that B cells, CD8+ T cell, CD4+ T cell, neutrophils, dendritic cells, CCL21, age (P=0), tumor stage (P=0), macrophage infiltration (P=0.035) and CCL8 (P=0.033) were associated with clinical outcomes of BC." (PMID 33146700, 2020). "However, in Cox multivariate analysis, after adjusting for clinical parameters such as ER, PR, Her2, grade, and tumor size, high CCL8 expression was not independently significantly associated with shorter DSS (HR = 1.16, p = 0.13)." (PMID 30930117, 2019). "Interestingly, TAMs in the hypoxic TME could also release CCL8 and thus cooperate with cancer cells to attract macrophages into the hypoxic area and promote tumour progression." (PMID 31263103, 2019). "The local CCL8-rich environment could promote the selection of tumor cells with metastatic ability." (PMID 26320180, 2015). "Tumor-associated macrophages (TAM) derive mostly from circulating monocytes which are attracted into tumor sites, by locally produced chemotactic factors, such as CCL2, CCL5, CCL7, CCL8, CXCL12, vascular endothelial growth factor (VEGF), and macrophage colony stimulating factor (M-CSF)." (PMID 24212934, 2011). "Recruited by tumour-derived chemokines such as CCL2, CCL5, and CCL8, TAMs are reprogrammed to enhance EMT, tumour motility, and metastasis, while hampering T-cell infiltration." (PMID 40361472, 2025). "In a KRAS-driven lung cancer model, the SASP secreted by senescent macrophages includes chemokines such as CCL2, CCL8, CCL7, CCL24, and CXCL13, which are involved in tumor cell metastasis." (PMID 39781471, 2025). "The release of pro-inflammatory chemokines and cytokines, such as IL-1, IL-2, IL-6, CCL-2, CCL-8, TNF-α and TGF-β, facilitate the recruitment of brain-resident immune cells to the tumour site." (PMID 41301734, 2025). "At the molecular level, transcription factors such as STAT1, CEBPB, HIF1A, and REL, collectively drive MDSCs expansion, while chemokines like CCL3, CCL4, CCL8 and IL1B regulate their migration within the tumor microenvironment." (PMID 41252877, 2025). "CA IX promotes tumor angiogenesis by inducing VEGF and other pro-angiogenic factors, while CA XII+ macrophages secrete CCL8, which recruits endothelial progenitor cells and synergistically enhances angiogenesis." (PMID 40422196, 2025). "Reciprocally, DMBT1 knockdown in LvM16 impaired the capacity of LvM16 CM to induce CD62L+ polarization and Ccl8 expression of primary KCs, leading to suppressed NET formation in vitro when neutrophils were co-cultured with tumor-pretreated KCs." (PMID 40796724, 2025). "The CCL chemokines CCL2, CCL7, CCL8, and CCL12 are known ligands for CCR2 expressed on circulating monocytes and facilitate their recruitment into the tumor microenvironment." (PMID 40867322, 2025). "TAMs are a major source of CCL8, which, together with SIGLEC1, participates in a tumour cell–TAM positive feedback regulatory loop that leads to increased tumour cell motility." (PMID 40434054, 2025).
tumor (continued). "Liver-tropic tumor cells induce CD62L-expressing KCs by a secretory protein DMBT1, and CD62L+ KCs activate neutrophils for NETosis via the chemokine CCL8." (PMID 40796724, 2025). "We identified CCL8 as a critical mediator of the GAS6/AXL/MERTK pathway, primarily by inhibiting Treg infiltration into the tumor." (PMID 39774471, 2025). "By combining diphtheria toxin with CCL8, DTCCL8 binds to multiple receptors on tumor cells and induces selective cytotoxicity." (PMID 40545574, 2025). "Notably, Vegfa macrophages and Proinflammatory macrophages exhibited downregulation of tumor angiogenesis and protumorigenic genes (e.g., Cxcl3, Cxcl1, S100a8, SPP1) and upregulation of immune cell recruitment‐associated genes (e.g., Cxcl9, Ccl5, Ccl8) in mRNA‐treated groups." (PMID 39761175, 2025). "M-MDSCs are mainly chemotactic through the binding of the CCR2 receptor with chemokines such as CCL2, CCL8, and CCL12, and they also play a variety of immunosuppressive and tumor-promoting roles in the TME." (PMID 40179015, 2025). "TAMs play a pivotal role in tumor progression by serving as the primary source of CCL8, whose interaction with SIGLEC1 orchestrates a positive feedback regulatory loop between tumor cells and TAMs, amplifying tumor cell motility." (PMID 39410029, 2024). "For example, M2 macrophages polarized under the effect of lactate produced by CRC cells released CCL8, which activated EMT genes in tumor cells via the CCL8/CCR5/70S6K/4EBP1 axis." (PMID 38794298, 2024). "CCL8 is a monocyte chemokine that can interact with CCR1, CCR2B, and CCR3; it also regulates tumor occurrence, antiviral infections, and inflammatory immunity in the host." (PMID 39185422, 2024). "Pro-inflammatory TAMs express TH1 response-inducing cytokines such as IL1α, IL1β, IL12 and TNFα while pro-tumor TAMs express IL10, CCL8, and CCL22 that are tumor promoting." (PMID 38802355, 2024). "For example, tumor secretion of TNF-α induces the chemokines CCL2 and CCL8 by TAMs which recruits additional CCR2+ monocytes to the TME." (PMID 37114134, 2023). "In support of these in vitro findings, the mRNA levels of CCL8 showed positive correlations with both GLUT1 and CA12 mRNA levels in HCC tumor tissue–purified monocytes." (PMID 35362480, 2022). "IL-33, Adiponectin, CCL8, GRO, and CCL2 contributed to the juxta-tumor type; the other analytes contributed to the tumor type." (PMID 36539890, 2022). "MSC exposure to tissue growth factor-beta (TGF-β) or challenging MSCs with monocyte chemotactic protein-1 (MCP-1), chemokine (C-C motif) ligand 8 (CCL-8), and/or interleukin 8 (IL-8) can increase the migration of MSCs towards the tumor." (PMID 35625723, 2022). "Hypoxia in the tumor microenvironment can promote the expression of transcription factor ZEB1, thereby upregulating CCL8 production by directly binding to the CCL8 promoter region." (PMID 35281057, 2022). "CCL8 secreted by TAMs recruits Tregs through CCR5, promoting tumor cell migration and invasion, leading to lung cancer metastasis." (PMID 35281057, 2022). "TAM-derived factors—such as CCL8, CCL5, and MMPs—play crucial roles in tumor invasion and progression by participating in ECM degradation." (PMID 34503065, 2021). "In BM+ tumor cells CCL20 exhibited a dramatic increase, while cytokines/chemokines such as CCL8, IL-6, and tumor necrosis factor superfamily members also showed an increasing trend." (PMID 34222020, 2021). "Identifying the sources of chemokines, CCL8 and CCL21 is critical for both targeting cancer cells and particularly modifying stromal and immune cells via tumor inhibitory mechanisms." (PMID 34160019, 2021). "Identifying the sources of the CCL8 and CCL21 in the tumor microenvironment and developing targeting strategies for these chemokines to prevent tumor growth will improve both prognosis and therapeutic outcomes." (PMID 34160019, 2021). "We found that cabozantinib treatment significantly upregulated CCL11, CCL12, CXCL12, CCL8 and CX3CL1 in the tumor microenvironment." (PMID 33954115, 2021).
tumor (continued). "Macrophages are attracted to tumor sites expressing chemotactic factors such as CCL7, CCL8 and CXCL12." (PMID 34001208, 2021). "The expression of CCL2 was upregulated 11.1-fold in tumor-adjacent tissue, and 5.3-fold in tumors compared to normal mucosa, in CCL7 2.3- and 1.9-fold, and in CCL8 8.3- and 2.1-fold." (PMID 34885960, 2021). "CCR5 binds many ligands which are overexpressed in the tumor microenvironment including CXCL13 (BCA-1), CCL3 (MIP1α), CCL3L1, CCL4 (MP-1β), CCL8 (MCP2), CCL11 (eotaxin), CCL13 (MCP-4), and CCL16 (HCC-4)." (PMID 33485378, 2021). "The results above showed that cabozantinib treatment increased the expression of CCL8 and CX3CL1 in the tumor environment, which is important for T cell migration." (PMID 33954115, 2021). "Mechanistically, we found that cabozantinib treatment induced expression of neutrophil-related chemokines (CCL11 and CXCL12) and T cell-related chemokines (CCL8 and CX3CL1) in the tumor microenvironment." (PMID 33954115, 2021). "Overall, these results indicate that tumor CD200 interacts with CD200R and limits the secretion of CCL8." (PMID 34692697, 2021). "Functional analysis demonstrated that CCL8 and CCL21 are involved in carcinogenesis, tumor immune escape mechanisms and chemoresistance in BC by several cancer-related kinases, miRNAs and transcription factors (ETS and E2F gene family)." (PMID 33146700, 2020). "Measurements of 36 different chemokines in the culture medium revealed a significant decrease in the secretion of CCL5, CCL8, CXCL1, CXCL2, CXCL5, and TGFβ1 and a significant increase in TGFβ2 secretion by TB9-Fhit transfected tumor cells." (PMID 32545680, 2020). "The results of correlation analysis between the expression of significant genes and tumor-infiltrating immune cells showed that the expression of CCL5, CCL8, CCR4, and CCR5 were all correlated with the level of tumor immune cell infiltration." (PMID 33181717, 2020). "TAMs influence on tumor cell invasiveness when tumor-released TNF-α elicits the expression and secretion of CCL8 from TAMs." (PMID 32499786, 2020). "Functional analysis demonstrated that CCL8 and CCL21 were involved in carcinogenesis, tumor immune escape and chemoresistance in BC." (PMID 33146700, 2020). "We demonstrated that TAMs are the major source of CCL8, and CCL8 and SIGLEC1 engage in a tumor cell-TAM regulatory loop, involving TNF-α, which in turn enhances their expression and leads to increased tumor cell motility." (PMID 30930117, 2019). "CCL8 and CCL2 secreted by tumor cells were reported to recruit monocytic cells, and CXCL1 and MIF were linked to the recruitment of MDSCs." (PMID 25514599, 2015). "First of all, the effect of CCL8 on dermal fibroblasts, melanocytes and CCR1-expressing tumor cell lines was examined, using MTT-test." (PMID 26320180, 2015). "Each of these chemokines was consistently expressed in all of the MCA-induced tumours tested and expression of most, namely CCL2, CCL7, CCL8, CCL12 and CX3CL1, was detectable only in the tumours and not in spleen and lymphoid tissue." (PMID 25495686, 2015). "In contrast, silencing of CCL8 suppressed only the recruitment of innate immune cells, while silencing of CCL7 reduced tumor cell proliferation almost to the levels observed in tumors growing in the absence of co-injected fibroblasts." (PMID 24068959, 2013). "Hypomethylated genes in the TNF network were cytokines (CCL3, CCL4, CCL7, CCL8, CCL22, IL21, IL17A, EBI3) that can either stimulate or inhibit tumor growth and progression." (PMID 22768131, 2012). "Eight of these immune response genes (SPP1, PDPN, IL1RN, IL6, CCL8, MDK, IRF7, and HRH4) were expressed between 1.25–1.59 fold higher in the microglia/macrophage enriched population compared to bulk tumor." (PMID 22937035, 2012). "In addition, ablation of tumor-infiltrating Tregs expressing CCR8, one of the primary receptors for CCL8, can elicit antitumor immunity and improve the efficacy of anti–PD-1 therapy." (PMID 39774471, 2025).
tumor (continued). "Whilst the expression of the Treg-associated chemokines, CCL8 and CCL16, was observed in non-immune cells, including epithelial cells (which includes the tumour cells), the highest expression of these chemokines was within the myeloid MoMac and DC populations." (PMID 39915477, 2025). "In addition, tumor-derived signals such as TNF-α induce TAMs to secrete chemokines (CCL2, CCL8) that recruit CCR2+ monocytes, amplifying the pro-tumoral milieu and enhancing immune evasion in NSCLC." (PMID 41584608, 2025). "The analysis revealed significantly higher expression levels of BASP1, FCGR1B, and FKBP11 in KIRC compared to normal adjacent tissues, while CCL8 showed no significant differential expression between tumor and non-tumor tissues." (PMID 40909125, 2025). "Similarly, in ovarian tumors, TNF-α is produced in large amounts, promoting a proinflammatory tumor microenvironment and activating NF-κB signaling, which induces the expression of chemokines including CCL8, CXCL13, and CXCL20 to accelerate tumor development." (PMID 38443657, 2024). "Inflammatory responses occur at the early stage after LITs, increasing the permeability of tumor vessels and promoting the injured tumor cells to produce chemokines (e.g., CCL2, CCL3, CCL4, CCL8, etc.)and proinflammatory cytokines (e.g., TNF-α, IL-1, IL-6, IL-17, etc.)." (PMID 36831664, 2023). "Thus, APN KO BMSCs highly migrate toward EL-4 tumor mass by CD44-HA interaction and recruit CD8+ T cells by releasing of CCL8." (PMID 37370133, 2023). "It is also worth investigating which ligands CCL8 binds to, including CCR1, CCR2, CCR3, and CCR5, and thus how it affects the downstream signaling pathways that lead to changes in the biological behavior of tumor cells." (PMID 36072582, 2022). "In the B16 melanoma metastasis model, MCP2/CCL8 exhibited direct repression of tumor cell proliferation or tumor cell invasion into surrounding normal tissue, confirming that MCP2/CCL8 possesses potential anti-tumor effect for tumor metastasis." (PMID 36034849, 2022). "Overall, with this bidimensional analysis we could show that tumor samples were well characterized by high secretions of IL-16, HGF, the TGF-β1, 2 and 3, SCF, FGF-2 and VEGF, and low secretions of CCL8 and Leptin." (PMID 36539890, 2022). "As chemokines, CCL8 and CCL5 are involved in tumor cell proliferation and metastasis." (PMID 34307121, 2021). "The CCL8 gene is only detected on monocytes/TAM and the DC cluster, whereas the CCL18 gene is expressed more widely on immune clusters (neutrophils, B cells, plasma cells and T cells) but, also, specifically, on tumor cell clusters from the lung tissue." (PMID 33924428, 2021). "The non-paired analysis confirmed significantly lower CCL2 and CCL8 expression in tumors compared to tumor-adjacent tissue." (PMID 34885960, 2021). "On the basis of these results, we hypothesize that the Apelin-induced CCL8 secreted by ECs provides a chemotactic signal to CD8+ and CD4+ T cells and promotes T cell extravasation from vessels and infiltration into the tumor." (PMID 34234274, 2021). "Interestingly, while the upregulation in tumors is markedly higher for CCL4 and CXCL2, the CCL2, CCL8 and CCL19 transcripts are relatively downregulated in tumors compared to tumor-adjacent tissue." (PMID 34885960, 2021). "More specifically CCL8 stimulates fibroblasts generating a pro-tumor environment in the TNBC stroma, which was not seen in non-TNBC43." (PMID 30850664, 2019). "Changes in expression levels of factors known to modulate tumor growth through immune recruitment (ie, CCL7, CCL8, ICAM) by resistance to death (ieTrxR, Trx, HIF‐1), and metastasis (ie, MMPs, ADAMs, ILs, Cts) may drive the inhibition observed." (PMID 31192543, 2019). "On the other hand, CCL8 as a chemoattractant either did not alter the migration of non-tumor cells or inhibited them (fibroblasts in low concentration)." (PMID 26320180, 2015).
tumor (continued). "These analyses revealed that the tumours are characterized by expression of inflammatory chemokines (CCL2, CCL5, CCL7, CCL8, CCL12, CXCL9, CXCL10 and CX3CL1), reflected by an enrichment of activated Foxp3− and Foxp3+ T cells expressing T helper type 1-associated chemokine receptors." (PMID 25495686, 2015). "Our results showed that cell cultures from the primary tumor did not express the chemokine while cells isolated from the circulation and metastases both expressed CCL8." (PMID 26320180, 2015). "Namely, cell cultures were created from metastatic and non-metastatic primary tumors, circulating tumor cells as well as lung metastases, and CCL8 expression was measured qualitatively." (PMID 26320180, 2015). "Several CC chemokine members, including CCL2 (MCP-1), CCL3 (MIP-1α), CCL5 (RANTES), CCL7 (MCP-3), CCL8 (MCP-2), CCL17 (TARC) CCL 20 (MIP-3α), CCL22 (MDC) and CCL23 (MPIF-1), are produced mainly by tumor infiltrating lymphocytes (TIL) and monocytes, and some of them also by cancer cells." (PMID 24213462, 2012). "However, a high ratio of CD8+ T cells within the tumor areas in relation to the total T cells in the stroma was correlated with the secretion of CXCR3 ligands (CXCL9, CXCL10 and CXCL11) and the CCR5 ligand CCL8." (PMID 35954489, 2022). "We found that CD200R-deficiency resulted in significantly upregulated production of CCL8, which could partially explain why tumor grows faster in the absence of CD200-CD200R interaction in TME." (PMID 34692697, 2021). "Furthermore, a negative correlation was obtained between CCL8 expression and BC tumor purity (Cor = −0.23, P=2.08e-13)." (PMID 33146700, 2020). "Upon tumour antigen pulsing, high levels of chemokines that sustain the recruitment of circulating DCs to inflamed tissues, such as CCL3, CCL4, were expressed, whereas at late time-points constitutive lymphoid chemokine such as CCL2, CCL8, CXCL10, CXCL12 and RANTES were selectively up-regulated." (PMID 26795765, 2016). "In vitro co-culture experiments using Yumm1.7 tumor cells with BMDM from WT and CD200R–/– mice confirmed upregulation of CCL8 in macrophages in the absence of CD200-CD200R interaction." (PMID 34692697, 2021). "In vitro co-culture experiments using Yumm1.7 tumor cells with bone marrow derived macrophages (BMDM) from WT and CD200R–/– mice confirmed upregulation of macrophage CCL8 in the absence of CD200-CD200R interaction." (PMID 34692697, 2021). "In light of these studies, we assume that upregulation of CCL8 in the absence of CD200R signaling plays a role in promoting tumor growth, which can partially explain the accelerated Yumm1.7 tumor growth observed in CD200R–/– mice." (PMID 34692697, 2021). "Maraviroc reduced Treg migration toward CCL8, and in vivo it reduced CCR5(+) Tregs and metastatic tumor burden in the lungs without affecting primary tumor growth." (PMID 32630699, 2020). "While no statistical differences in IL-1β, CCL-7, CCL-8, CCL-24 and CXCL-5 gene expression were confirmed among four tumor groups." (PMID 24260500, 2013). "By comparing metastasis-related genes expressed in paired nontumor tissue– and tumor tissue–purified monocytes, we found that levels of MMP9, VEGFA, and CCL8 were all increased in the tumor monocytes compared with the nontumor monocytes, with CCL8 exhibiting the most marked upregulation." (PMID 35362480, 2022).